C3 (complement C3)
Diseases named in the same sentence as C3 in open-access papers (continued):
Sharing a sentence is not in itself a finding about the gene and the disease.
memory impairment (4 papers, 2017 to 2025). "Considering that immune system function alters with age, there is a need to explore the connections of complement C3 in the innate immune system with age‐related learning and memory impairments." (PMID 40539508, 2025). "Age‐related complement C3 elevation induces memory impairments and neuropathology by dysregulating astrocytic insulin signaling and triggering mitochondrial dysfunction." (PMID 40539508, 2025). "However, it remains unclear whether increased complement C3 expression directly contributes to learning and memory impairments." (PMID 40539508, 2025). "However, it remains unclear whether complement C3 serves as a core molecule that drives learning and memory impairments and what molecular mechanisms might be involved." (PMID 40539508, 2025). "Notably, by blocking complement C3 in the brains of SAMP8 mice using antibodies, we were able to effectively reverse these learning and memory impairments." (PMID 40539508, 2025).
minimal change disease (4 papers, 2016 to 2026). "Renal biopsy revealed features consistent with minimal change disease, and immunofluorescence was negative for IgG, IgM, IgA, C3, and C4." (PMID 41626137, 2026).
neuroblastoma (4 papers, 2015 to 2023). Neuroblastoma (NB) is the most common solid, extracranial childhood tumor. "Interestingly, in a previous microarray analysis performed by our group using the neuroblastoma cell line TR overexpressing C/EBPβ, we also identified C3 as a gene regulated by C/EBPβ." (PMID 25617152, 2015). "There was constitutive expression of complement factor B, C3, C5 and C9 in SH-SY5Y neuroblastoma cell lines stably expressing the NOTCH3 receptor." (PMID 37158955, 2023).
neuropathy (4 papers, 2012 to 2025). A disorder affecting the nervous system that manifests with pain, tingling, numbness, and/or muscle weakness. "Complement C3 has been associated with increased risk of neuropathy, suggesting that it may have a proinflammatory role that limits the nerve regeneration capacity." (PMID 40828619, 2025). "The complement system may also contribute to compromised microvascular function, and activation of complement, including C3, may thus contribute to the diabetic nephropathy, retinopathy and neuropathy." (PMID 22282163, 2012). "Based on these data and previous studies implicating complement, specifically C3, in other neuropathies, we hypothesized that complement activation was, at least in part, triggering the deafening-related immune response and/or directly contributing to SGN death after hair cell loss." (PMID 38840777, 2024).
ovarian tumors (4 papers, 2002 to 2025). "Increased C3 expression was observed in omental implants compared with primary ovarian tumors and C3 secretion was higher in OC ascites from high-BMI versus low-BMI patients." (PMID 39964754, 2025). "Conversely, antitumor T cells require the production of C3 and the release of C5a in the endothelium in order to infiltrate ovarian tumors." (PMID 34359708, 2021). "Genetic or pharmacological inhibition of C3 or C5aR1 results in smaller and poorly vascularized ovarian tumors in vivo, and C5a is able to promote endothelial cell tube formation and migration." (PMID 34359708, 2021).
Pancytopenia (4 papers, 2021 to 2025). An abnormal reduction in numbers of all blood cell types (red blood cells, white blood cells, and platelets). "She had pancytopenia, an erythrocyte sedimentation rate of 92, positive antinuclear antibody titer, and high anti-double-stranded deoxyribonucleic acid (DNA), with low C3 and C4 complements." (PMID 34176492, 2021).
parasitemia (4 papers, 2016 to 2025). "Complement associated phagocytosis has also been described for T. brucei, and more recently the use of C3 knock-out mice confirmed a role for complement in peak parasitemia clearance during T. brucei infections." (PMID 32218784, 2020). "brucei/ml blood depending on mutant mouse strain on day 6 after infection and, with the exception of mice lacking the gene encoding complement factor 3 (C3-/-), remitted first wave parasitemia to a level of <106T." (PMID 27403737, 2016). "Despite clearance of parasitemia, the patient developed worsening hemolysis characterized by a complement C3-positive, immunoglobulin (IgG)-negative direct antiglobulin test, consistent with complement-mediated hemolysis; cold agglutinin titer was negative." (PMID 41220440, 2025).
primary immunodeficiency (4 papers, 2015 to 2025). "Of note, C3 also significantly showed a positive association with primary immunodeficiency, PD-L1 expression and the PD-1 checkpoint pathway, raising the possibility that resident or chemotaxis CD8+ T cells in C3 may represent a dysfunctional continuum." (PMID 39905449, 2025). "It was also shown that C3 transcription is LFA-1 (lymphocyte function-associated antigen 1)-dependent, and perturbations in the LFA-1-C3-axis contribute to primary immunodeficiency." (PMID 36969185, 2023).
renal carcinoma (4 papers, 2020 to 2026). A carcinoma arising from the epithelium of the renal parenchyma or the renal pelvis. "Using the co-expression tool on expression data extracted from renal cancer cell samples of CCLE, we obtained lists of genes that were co-expressed with FN1, C3, and C3AR1 and harbored a correlation coefficient > 0.5 or < − 0.5 and P-value < 0.01." (PMID 34688260, 2021).
retinopathy of prematurity (4 papers, 2020 to 2023). A bilateral retinopathy characterized by neovascularization, scarring, retinal detachment, and eventually blindness. "C3 has shown an anti-angiogenic role in a model of retinopathy of prematurity (ROP): it was found that mice deficient in C3 displayed increased neovascularization in this model and in the in vivo Matrigel plug assay." (PMID 37296948, 2023). "Like factor B knockouts in the OIR model, C3-deficient mice displayed increased neovascularization in the model of retinopathy of prematurity (ROP) and in an in vivo matrix plug assay." (PMID 33271774, 2020).
septic arthritis (4 papers, 2016 to 2025). "C3 and fB deficiencies alter serum cytokine profiles in mice with hematogenous S. aureus septic arthritis." (PMID 26787717, 2016). "We conclude that C3 deficiency increases susceptibility to hematogenous S. aureus septic arthritis and impairs host bacterial clearance, conceivably due to diminished opsonization and phagocytosis of S. aureus." (PMID 26787717, 2016). "In this study, we demonstrated that C3 deficiency significantly increased both the frequency and severity of S. aureus hematogenous septic arthritis in mice." (PMID 26787717, 2016). "Our data demonstrate that C3 deficiency greatly increased susceptibility to staphylococcal hematogenous septic arthritis." (PMID 26787717, 2016). "C3 deficiency increases the severity and frequency of hematogenous septic arthritis." (PMID 26787717, 2016). "To study the roles of C3 and fB in the late stage of septic arthritis, we injected S. aureus into the knee joints of NMRI (The Naval Medical Research Institute) mice to bypass the early immune responses in the bloodstream." (PMID 26787717, 2016). "Taken together, these results show that C3-mediated opsonization of S. aureus is critical for host defense against S. aureus hematogenous septic arthritis." (PMID 26787717, 2016). "Our data demonstrate the essential protective role of C3-mediated opsonization in host defense against S. aureus hematogenous septic arthritis and raise the possibility of enhancing C3 function for new antistaphylococcal treatments." (PMID 26787717, 2016). "Taken together, these results show that C3-mediated opsonization plays a critical role in protecting the host against S. aureus septic arthritis." (PMID 26787717, 2016). "Recent data from our lab show that mice lacking the complement component 3 (C3-/-) are highly susceptible to S. aureus septic arthritis." (PMID 33546401, 2021). "In the present study, we compared the susceptibilities to S. aureus septic arthritis of mice lacking C3, complement factor B (fB), and receptor for C3-derived anaphylatoxin C3a (C3aR) using our well-established murine models for S. aureus arthritis." (PMID 26787717, 2016). "C3aR deficiency had no impact on the development of hematogenous septic arthritis, suggesting that the observed effects of C3 deficiency in hematogenous septic arthritis are largely due to impaired opsonization mediated by C3b rather than C3a-induced proinflammatory responses." (PMID 26787717, 2016).
septic shock (4 papers, 2011 to 2023). Shock caused by infection; frequently caused by gram negative bacteria, although some cases have been caused by other bacteria, viruses, fungi, and protozoa; characterized by fever, chills, tachycardia, tachypnea, and hypotension. "Similarly, the septic shock patients had significantly lower levels of C3, and higher levels of soluble TCC in their plasma, than the non-septic patients, who also differed significantly from the controls." (PMID 32082310, 2020).
squamous cell carcinoma (4 papers, 2017 to 2024). A carcinoma arising from squamous epithelial cells. "In summary, our data show that C3 drives squamous carcinoma cell tumorigenesis during chronic skin inflammation, independently of the downstream generation of C5a or MAC." (PMID 32682912, 2021). "CFH co-factor for complement factor 1 inhibits C3 activation cascade in alternative pathway by promoting cleavage of C3b to iC3b-over-expression has been reported in cutaneous squamous cell carcinoma cells." (PMID 30100996, 2018). "In a recent study conducted by Koifman the authors demonstrate through proteomic analysis, the absence of human complement C3 in samples of patients with squamous cell carcinoma of the penis." (PMID 24893913, 2017).
thrombotic thrombocytopenic purpura (4 papers, 2020 to 2026). "Infectious causes and thrombotic thrombocytopenic purpura (TTP) were excluded, and persistently low complement C3 levels supported complement activation." (PMID 41383869, 2025). "Ravulizumab was started on day 2 after thrombotic thrombocytopenic purpura and Shiga toxin-associated HUS were excluded, and aHUS was clinically suspected on the basis of isolated C3 hypocomplementemia." (PMID 41680667, 2026). "Workup for thrombotic thrombocytopenic purpura (TTP), HUS, heparin-induced thrombocytopenia was grossly negative on this admission, including ADAMTS13 activity (43%), C3 level (154 mg/dL), C4 level (41 mg/dL), negative heparin platelet antibody and a peripheral blood smear negative for schistocytes." (PMID 32481360, 2020).
xerostomia (4 papers, 2017 to 2021). Dryness of the mouth resulting from reduced salivary secretion. "And sSS patients showed higher total ESSPRI score and higher prevalence of xerostomia and low C3, C4 levels with more liver, articular involvement and saliva gland atrophy, and more severe lymphocyte infiltration in salivary glands than pSS patients." (PMID 29703151, 2018).
acute coronary syndrome (3 papers, 2013 to 2025). Signs and symptoms related to acute ischemia of the myocardium secondary to coronary artery disease. "We also measured the C3/C4 ratio given recent data associating increased serum C3/C4 ratio as a novel marker for recurrent cardiovascular events in acute coronary syndrome." (PMID 40276257, 2025). "In acute coronary syndrome (an inflammatory disease), the complement cascade is activated and the C3 and C4 concentration ratio (C3/C4 ratio) in serum is a readily available marker of recurrent cardiovascular events." (PMID 24063402, 2013). "In pathological states, including acute coronary syndromes, the levels of apoA-IV and haemoglobin beta were demonstrated to be diminished, while levels of serum amyloid A (SAA) and complement C3 (C3) were markedly increased." (PMID 34572269, 2021).
acute myeloid leukemia (3 papers, 2019 to 2023). Acute myeloid leukemia (AML) is a group of neoplasms arising from precursor cells committed to the myeloid cell-line differentiation. "C3 and LAIR1((INK4a))genes were both detected, which were shown to be related to acute myeloid leukemia." (PMID 31533352, 2019).
airway hyperresponsiveness (3 papers, 2005 to 2025). "Complement modulation (C3 deficiency) has, in turn, been leveraged to decrease exposure-generated inflammation in a murine model of particulate matter-induced lung/ airway hyperresponsiveness." (PMID 30395590, 2018).
allergic rhinitis (3 papers, 2011 to 2025). Inflammation of the nasal mucous membranes caused by an IgE-mediated response to external allergens. "C3, A2M, APOA1, and APOA2 were also found to be significantly more abundant in nasal mucus in allergic rhinitis patients in our previous studies." (PMID 32266843, 2020).
Alport syndrome (3 papers, 2014 to 2024). A rare renal disease characterized by glomerular nephropathy with hematuria progressing to end-stage renal disease (ESRD), frequently associated with sensorineural deafness, and occasionally with ocular anomalies. "Nonspecific trapping of IgM and C3 was observed by IF in cases of FSGS, while the IF was negative in MCD, TBMD and Alport’s syndrome." (PMID 28197459, 2014).
aneurysm (3 papers, 2021 to 2025). Bulging or ballooning in an area of an artery secondary to arterial wall weakening. "Our data also demonstrate that in smooth muscle cells of people with aneurysms, there is an increase in the expression of the C3 gene, which leads to the phenotypic modulation of SMCs to a synthetic phenotype and the development of inflammation." (PMID 40695950, 2025). "We also found lower deposition of complement C3 (activated by classical, alternative and lectin pathways) and C9 (member of membrane attack complex), which are critical mediators of aneurysm." (PMID 34323424, 2021).
anorexia nervosa (3 papers, 2011 to 2019). A disorder most often seen in adolescent females characterized by a refusal to maintain a minimally normal body weight, an intense fear of gaining weight, a disturbance in body image, and, in postmenarcheal females, the development of amenorrhea. "Serum complement C3 levels were found to be decreased in anorexia nervosa compared to the controls (p < 0.001) in a small study (n = 14), but 50% hemolytic complement activity (CH50) was not statistically different." (PMID 31717370, 2019). "In a prospective cohort study on 14 patients with severe anorexia nervosa having BMI less than 14.0, serum complement C3 levels were found significantly lower than in the healthy controls." (PMID 22545044, 2012). "Serum C3 levels were significantly lower in patients with anorexia nervosa than in controls (median 3.7 (interquartile range (IQR) 2.5-4.9) vs 11.4 (IQR 8.9-13.7, P <0.001)." (PMID 21542928, 2011). "This study provides first evidence of significantly decreased complement C3 levels in patients with severe anorexia nervosa, compared to healthy control subjects." (PMID 21542928, 2011). "Serum levels of C3 were threefold lower in patients with anorexia nervosa than in controls (median 3.7 (interquartile range (IQR) 2.5-4.9) vs 11.4 (8.9-13.7), P <0.001)." (PMID 21542928, 2011). "The present study was designed to evaluate the role of complement C3 levels, the extent of complement activation and of complement hemolytic activity in serum, as potential new biomarkers for the severity of anorexia nervosa." (PMID 21542928, 2011). "That is, in patients with anorexia nervosa and severely low body weight, in whom basic laboratory tests are often normal, low serum C3 levels can confirm biochemical evidence of severe illness." (PMID 21542928, 2011). "Similarly, serum complement C3 (p < 0.001), along with C1q (p < 0.05) and C2 (p < 0.001), were all low in the anorexia nervosa group of another study (n = 14), but with normal serum levels of C4, C5, and C6 when compared to the controls." (PMID 31717370, 2019). "Complement C3 serum levels may represent a sensitive new biomarker for monitoring the severity of disease in anorexia nervosa." (PMID 21542928, 2011). "We hypothesized that anorexia nervosa results in complement activation and consumption of complement C3, the central component of all complement activation pathways." (PMID 21542928, 2011). "Serum samples were obtained from anorexia nervosa patients in a biweekly manner after initiation of refeeding and analyzed for levels of CH50, C3, C3a, C5a and sC5b-9." (PMID 21542928, 2011). "The fact that serum C3 levels did not statistically correlate with weight restoration over the course of treatment may have a complex explanation, and thus restoration of non-edematous weight remains the best marker of physiologic recovery in anorexia nervosa." (PMID 21542928, 2011).
Arterial thrombosis (3 papers, 2015 to 2024). The formation of a blood clot inside an artery. "In vivo studies with C3 knockout models confirmed reduced platelet aggregation and less venous and arterial thrombosis in mice, with the platelet activation mechanism subsequently demonstrated to be due to binding of C3a to the platelet C3a receptor (C3aR)." (PMID 38337435, 2024). "Moreover, some studies have described deposits of Ig, C1q and C3 in the heart valves of patients with aPL-associated valvulopathy, in renal biopsies of patients with APS nephropathy and in a male patient who underwent bypass surgery after which he developed arterial thrombosis." (PMID 36172349, 2022).
arteriosclerosis (3 papers, 2021 to 2023). A vascular disorder characterized by thickening and hardening of the walls of the arteries. "Deposition of C3, presence of arterial sclerosis, and endothelial cell injury were present in patients in this LPHS cohort but similar abnormalities have been reported in studies of healthy kidney donors." (PMID 37180518, 2023). "Nevertheless, it is known that the complement activation and C3, as the connector between the activation pathways and effector mechanisms, is involved in cardiovascular diseases such as arteriosclerosis." (PMID 34071589, 2021). "However, the ORs for C3 deposits in the presence of IFTA (scores 2–3), interstitial inflammation (score 2), arteriolar hyalinosis (score 2), and arteriosclerosis (score 2) were 1.19 (95% CI, 0.63–2.26), 1.48 (95% CI, 0.79–2.78), 0.79 (95% CI, 0.4–1.58), and 1.52 (95% CI, 0.78–2.99), respectively." (PMID 35711407, 2022).
Ascites (3 papers, 2019 to 2025). Accumulation of fluid in the peritoneal cavity (between the layers of the peritoneum that lines the abdomen). "Interestingly, the active (cleaved) form of C3 (C3a) was detectable at higher levels in OC-associated ascites compared with plasma from the same patients." (PMID 39964754, 2025).
autism spectrum disorder (3 papers, 2021 to 2025). A spectrum of developmental disorders that includes autism, and Asperger syndrome. "Recent findings of social interaction deficits and repetitive behavior induced by C3 knockdown in the prefrontal cortex of adult mice provide support for to a role of C3 deficiency in the pathophysiology of autism-spectrum disorder." (PMID 33692783, 2021). "In the developing brain, C3aR and C3 have been shown to play a role in neural progenitor cell proliferation and neuronal migration with potential implications for autism spectrum disorder, and adult C3aR deficient (C3aR−/−) mice were reported to exhibit subtle deficit in recall memory." (PMID 33692783, 2021).
Brain atrophy (3 papers, 2022 to 2025). Partial or complete wasting (loss) of brain tissue that was once present. "We hypothesized that serum‐derived EVs from r‐DMV participants promote brain atrophy by regulating inflammation‐related proteins, particularly by downregulating C3 and upregulating SERPINA3." (PMID 37438638, 2023).